IGKV2-26 (immunoglobulin kappa variable 2-26 (pseudogene))
Synonyms: A21; IGKV226
Gene: Immunoglobulin variable (V) pseudogene on chromosome 2 (89,196,096 to 89,196,829, reverse strand). Ensembl gene ENSG00000254098.
Diseases named in the same sentence as IGKV2-26 in open-access papers:
IGKV2-26 is named in the same sentence as 1 disease in open-access papers, as found by Europe PMC text mining. Sharing a sentence is not in itself a finding about the gene and the disease.
IGKV2-26 shares sentences with these, for which no sentence is quoted: diabetes (1 paper).